MYOD1 (myogenic differentiation 1)
Description:
Acts as a transcriptional activator that promotes transcription of muscle-specific target genes and plays a role in muscle differentiation. Together with MYF5 and MYOG, co-occupies muscle-specific gene promoter core region during myogenesis. Induces fibroblasts to differentiate into myoblasts. Interacts with and is inhibited by the twist protein. This interaction probably involves the basic domains of both proteins (By similarity).
Synonyms: bHLHc1; MYF3; MYOD; PUM; CMYO17; CMYP17; MYODRIF
Tractability: PROTAC: UniProt records ubiquitination sites on it.
Gene: Protein-coding gene on chromosome 11 (17,719,571 to 17,722,136, forward strand). Ensembl gene ENSG00000129152.
Subcellular location: Nucleus
Subcellular location (Human Protein Atlas): Nucleoplasm
Pathways (Reactome):
Chromatin organization: CHD1 and CHD2 subfamily
Developmental Biology: Myogenesis
Signal Transduction: TGFBR3 expression
Gene Ontology:
Molecular function: DNA-binding transcription activator activity, RNA polymerase II-specific; nuclear receptor binding; protein binding; RNA polymerase II transcription regulatory region sequence-specific DNA binding; sequence-specific double-stranded DNA binding; chromatin binding; DNA-binding transcription activator activity; DNA-binding transcription factor activity, RNA polymerase II-specific; E-box binding; promoter-specific chromatin binding; RNA polymerase II cis-regulatory region sequence-specific DNA binding; RNA polymerase II-specific DNA-binding transcription factor binding; bHLH transcription factor binding; chromatin DNA binding; cis-regulatory region sequence-specific DNA binding; DNA binding; DNA-binding transcription factor activity; enzyme binding; protein dimerization activity; protein homodimerization activity; sequence-specific DNA binding; ubiquitin protein ligase binding
Biological process: myotube cell development; positive regulation of muscle cell differentiation; positive regulation of myoblast fusion; positive regulation of transcription by RNA polymerase II; protein unfolding; regulation of RNA splicing; cellular response to estradiol stimulus; muscle cell fate commitment; muscle organ development; positive regulation of myoblast differentiation; positive regulation of skeletal muscle fiber development; positive regulation of snRNA transcription by RNA polymerase II; regulation of transcription by RNA polymerase II; skeletal muscle cell differentiation; skeletal muscle tissue development; animal organ development; muscle cell differentiation; regulation of DNA-templated transcription; regulation of gene expression; skeletal muscle tissue regeneration; tissue development
Cellular component: ATPase complex; nucleoplasm; chromatin; euchromatin; nucleus; RNA polymerase II transcription regulator complex; transcription regulator complex; cytoplasm; myofibril
Genetic constraint (gnomAD): Loss-of-function variants: 15 observed, 12.81 expected, observed/expected ratio (o/e) 1.17, 90% interval 0.78 to 1.75. The upper end of that interval is the gene's LOEUF score, 1.75, which puts it in group 6 of 6, group 1 being the genes least tolerant of losing a copy. Missense variants: 529 observed, 446.52 expected, observed/expected ratio (o/e) 1.18, 90% interval 1.1 to 1.27. Synonymous variants: 235 observed, 195.96 expected, observed/expected ratio (o/e) 1.2, 90% interval 1.08 to 1.34.
Cancer hallmarks: suppression of growth (promotes); invasion and metastasis (suppresses); escaping programmed cell death (promotes); change of cellular energetics; angiogenesis (suppresses); escaping programmed cell death (suppresses); genome instability and mutations (suppresses)
Homologues: Orthologues: chimpanzee MYOD1 (99% identical), macaque MYOD1 (97% identical), pig MYOD1 (93% identical), dog MYOD1 (93% identical), guinea pig MYOD1 (91% identical), mouse Myod1 (88% identical), rat Myod1 (87% identical), rabbit MYOD1 (81% identical), zebrafish myod1 (59% identical), tropical clawed frog MYOD1 (56% identical), Drosophila melanogaster nau (30% identical), Caenorhabditis elegans hlh-1 (26% identical). Paralogues in human: MYF5 (39% identical), MYF6 (28% identical), MYOG (26% identical).
Diseases named in the same sentence as MYOD1 in open-access papers:
MYOD1 is named in the same sentence as 181 diseases in open-access papers, as found by Europe PMC text mining. Sharing a sentence is not in itself a finding about the gene and the disease. The quoted sentences say what the papers report.
rhabdomyosarcoma (119 papers, 1991 to 2026). A rare aggressive malignant mesenchymal neoplasm arising from skeletal muscle. "The myogenic differentiation 1 gene (MYOD1) p.L122R mutation was first discovered in a subset of clinically aggressive rhabdomyosarcomas in both adults and children." (PMID 36980529, 2023). "We validated Pax3-Foxo1 expression in three ACP tumors, none of which expressed the myogenic regulatory transcription factors Myod1 or Myog that are diagnostic for rhabdomyosarcoma." (PMID 37968277, 2023). "Whole-exome sequencing of rhabdomyosarcomas led to the identification of a recurrent mutation in the MYOD1 gene in the embryonal subtype, which is associated with a bad prognosis." (PMID 37998367, 2023). "To generate REVec encoding MyoD1, we cloned MyoD1 cDNA from human rhabdomyosarcoma cell line TE671 in REVec vector plasmid containing GFP as a marker." (PMID 31309127, 2019). "A hallmark of rhabdomyosarcoma is that tumors express early markers along the skeletal muscle lineage such as MYOD1, MYOG and Desmin; however, these tumors fail to terminally differentiate indicating a developmental arrest." (PMID 29869612, 2018). "Taken together, we present the first report of MYOD1 (L122R) mutation in the largest cohort of 49 rhabdomyosarcomas reported so far, that are associated with a relatively aggressive clinical course." (PMID 27562493, 2016). "If the patient is accompanied by heterologous sarcoma components, such as rhabdomyosarcoma components with positive expressions of Desmin, Myogenin, and MyoD1, the risk of recurrence may increase." (PMID 38783282, 2024). "For example, MDM2 amplification is present in most dedifferentiated liposarcomas and typically co-amplified with CDK4 and/or HMGA2, synovial sarcomas (SS) are often characterized by SS18–SSX fusions, and presence of MYOD1 mutations indicate spindle cell/sclerosing rhabdomyosarcoma." (PMID 35053600, 2022). "We analyzed a much larger cohort of 49 primary rhabdomyosarcoma tumor samples of various subtypes, collected over a period of 9 years, for the presence of MYOD1 (L122R), PIK3CA (H1047), and PIK3CA (E542/E545) mutations, along with immunohistochemical analysis of desmin, myogenin, and MYOD1." (PMID 27562493, 2016). "Both cell lines demonstrated histological features, respectively, corresponding to the implanted embryonal or alveolar variants of rhabdomyosarcoma, including nests of small round blue cells with fibrovascular septae and positive MyoD1 and Myogenin immunochemistry." (PMID 21559211, 2011). "Immunohistochemical(IHC) staining confirmed diffuse positivity for skeletal muscle lineage markers(desmin, myogenin, MyoD1) in the tumor cells, thereby establishing a definitive diagnosis of rhabdomyosarcoma." (PMID 41783407, 2026). "Rhabdomyosarcoma expresses desmin, MyoD1, or myogenin due to skeletal muscle differentiation, whereas small cell carcinoma expresses CK and CgA with or without Syn." (PMID 40978053, 2025). "Spindle cell/sclerosing rhabdomyosarcomas typically harbor certain genomic alterations, including rearrangements involving TFCP2, VGLL2, NCOA2, CITED2, TEAD1, and SRF, as well as the MYOD1 p.L122R mutation." (PMID 40361368, 2025). "In contrast, our case was negative for myogenic markers such as desmin, caldesmon, calponin, and MyoD1, as well as for the IMT-associated marker ALK, supporting the exclusion of leiomyosarcoma, rhabdomyosarcoma and IMT." (PMID 40936706, 2025). "Literature reports indicate that MyoD1 plays a critical role in muscle development and differentiation and is vital in various diseases such as rhabdomyosarcoma and gastric cancer." (PMID 39242558, 2024). "Immunohistochemical findings for alveolar rhabdomyosarcoma include the following: tumour cells expressing myogenic markers such as Des and MyoD1, with MyoD1 observable in the nucleus, which differs from the cytoplasmic positivity observed in ASPS cells." (PMID 38291475, 2024).
rhabdomyosarcoma (continued). "Every observed tumor cell showed a strong nuclear MyoD1 staining, which is indicative of a rhabdomyosarcoma (RMS) 4,5." (PMID 37349371, 2023). "MyoD1 staining (heterogeneously expressed in embryonal rhabdomyosarcoma) was considered ambiguous in the bone marrow aspirate." (PMID 37664065, 2023). "In the case of human rhabdomyosarcoma cells, it resulted in increase of MYOD1, MYOG, and MyHC expression." (PMID 34571854, 2021). "For example, when comparing MYOD1 and NEUROD2 binding in P19 cells vs. fibroblasts and MYOD1 also in myotubes vs. rhabdomyosarcoma cells." (PMID 34502060, 2021). "Positive staining for skeletal muscle differentiation markers such as myoD1 and myogenin along with cross-striation are distinctive findings in rhabdomyosarcoma." (PMID 34162402, 2021). "Pleomorphic rhabdomyosarcoma shows at least focally an expression of skeletal muscle-specific markers, i.e., myoglobin, MyoD1, or myogenin, and lacks positivity for melanocytic markers." (PMID 31309284, 2020). "In rhabdomyosarcoma, MYOD1 is expressed in small, primitive tumor cells, whereas cells that exhibit morphological evidence of skeletal muscle differentiation generally lack MYOD1 expression." (PMID 31941033, 2020). "Rhabdomyosarcomas show rhabdomyoblasts or alveolar architecture and are positive for myogenin and MyoD1." (PMID 32316685, 2020). "Recently, it has been suggested that MYOD1 regulates common gene programs that lock cells in an arrested myogenic fate and is required for the self-renewal of rhabdomyosarcoma cells and sustained tumor growth." (PMID 31941033, 2020). "Epithelioid rhabdomyosarcomas are positive for specific markers of skeletal muscle differentiation (e.g., myogenin, MyoD1)." (PMID 32316685, 2020). "Corroborating the increase in the expression of CDH15 along with MYOD1 in our model of rhabdomyosarcoma CSCs, MYOD1 knockdown has been demonstrated to significantly downregulate CDH15 expression." (PMID 31941033, 2020). "We observed that the rhabdomyosarcoma cell lines expressed their signature markers MYOD1 as well as downstream myogenic genes MYOGENIN and DESMIN." (PMID 30446688, 2018). "Similar to its activity in immortalized human myoblasts, DUX4 was able to downregulate MYOD1 expression in the rhabdomyosarcoma cell lines." (PMID 30446688, 2018). "Small numbers of these cases were assigned provisional diagnoses, for example, rhabdomyosarcoma, if there was focal expression of appropriate markers (e.g., clear cut desmin with myogenin or MyoD1)." (PMID 25810689, 2015). "Negativity for myogenin and myoD1 expression is seen, and these markers differentiate synovial sarcomas from rhabdomyosarcomas." (PMID 26101678, 2015). "Of the 36 tumors, 2 (5.5%) had positive results for desmin and coexpressed nuclear myoD1, confirmed the diagnosis of rhabdomyosarcoma." (PMID 24349741, 2013). "Commitment and maintenance of skeletal muscle differentiation during normal skeletal muscle myogenesis, as well as in Rhabdomyosarcoma, is regulated by a family of closely related genes (eg. myoD1, myogenin, myf-5, MRF-4), termed the MyoD family." (PMID 24455040, 2012). "MyoD1 and myogenin are considered useful markers in diagnosing Rhabdomyosarcomas and for differentiating it from other soft tissue tumors." (PMID 24455040, 2012). "MYOD1 has been recently implicated in myoblast maintenance, and, in combination with TCF3, it inhibits myoblast differentiation leading to Rhabdomyosarcomas." (PMID 20500816, 2010). "Contrarily, pediatric cases of sclerosing rhabdomyosarcoma expressed strong immunopositivity for all muscle markers, including MyoD1, Myogenin, Desmin and SMA, most likely reflecting a different stage of muscle maturity." (PMID 20701800, 2010). "For example, myogenin and myoD1 are specific and sensitive for the diagnosis of rhabdomyosarcoma and lymphoid markers such as CD20, CD3, CD30 and CD45 are very useful in the diagnosis of lymphoma." (PMID 20598147, 2010).
rhabdomyosarcoma (continued). "Here, we show that recurrent L122R mutation (Leucine to Argine change at amino acid 122) in the DNA-binding site of the Myogenic Differentiation 1 (MYOD1) transcription factor increases cancer stem cell frequency in aggressive Spindle cell/sclerosing rhabdomyosarcoma." (PMID 42236477, 2026). "Immunohistochemistry showed positivity for rhabdomyosarcoma markers such as Desmin, MyoD1, and Myogenin in the rhabdomyosarcomatous component and positivity for neuroectodermal markers, including synaptophysin and chromogranin A in the neuroectodermal component." (PMID 41465905, 2025). "In contrast, MyoD1 and myogenin demonstrate both high specificity and sensitivity for diagnosing RMS, with positive staining localized in the nucleus, making them reliable diagnostic markers for rhabdomyosarcoma." (PMID 40703554, 2025). "However, MyoD1 is a specific marker for rhabdomyosarcoma, and its cytoplasmic expression in ASPS is often regarded as a false-positive due to variability in antibody clones." (PMID 40176092, 2025). "In contrast, rhabdomyosarcomas express MyoD1 and myogenin, which help in differentiation." (PMID 41185734, 2025). "Early on, it was suggested that ASPS may originate from rhabdomyosarcoma due to the cytoplasmic expression of MyoD1 found in tumor cells of ASPS." (PMID 40176092, 2025). "After completing the histopathological examination, we established the diagnosis of IS and found areas of rhabdomyosarcoma differentiation microscopically, which was supported by the focal positivity of immunohistochemistry for MyoD1 and myogenin, which is rare in cardiac IS." (PMID 38835391, 2024). "Desmin, myogenin, and MyoD1 help identify rhabdomyosarcoma components." (PMID 39450250, 2024). "Historically, rhabdomyosarcoma at our center has been more of a morphological diagnosis with further validation of diagnosis and or subtype by using immunohistochemical stains such as Desmin, Myogenin, and myoD1." (PMID 35942988, 2023). "Detection of MID for rhabdomyosarcoma included myogenins, MyoD1 and PAX-FOXO1 fusion transcript, for synovial sarcoma—Bcl-2 protein and SYT-SSX fusion transcript, for clear cell sarcoma—S100 and melanoma cocktail and EWS-ATF1 fusion transcript by IHC and RT-qPCR." (PMID 37686475, 2023). "Moreover, MYOD1 immunostaining revealed multifocal positivity in the present case, in contrast to diffuse staining that is reported in most spindle cell/sclerosing rhabdomyosarcomas." (PMID 35642345, 2023). "Rhabdomyosarcomas expressed vimentin, desmin, myoD1, and myogenin." (PMID 35001360, 2022). "The cell of origin of this subtype is unknown but rhabdomyosarcoma cells usually show variable skeletal muscle lineage differentiation and/or are positive for skeletal muscle differentiation proteins like myogenic differentiation 1 (MyoD1) or myogenin." (PMID 34957097, 2021). "Of note, all models except for IRS-68 overexpress the common rhabdomyosarcoma biomarker, MYOD1." (PMID 31693904, 2019). "In those cases of ESFTs which display focal positivity for S100 or desmin, additional immunohistochemical stains for melanoma markers (HMB45, Melan-A) and specific skeletal muscle markers (myogenin, myoD1) can be utilized to exclude melanoma and rhabdomyosarcoma." (PMID 27413360, 2016). "Moreover, some specific immunohistochemistry markers which were not known to be expressed in ALCL but in the other malignancies can support the diagnosis, including rhabdomyosarcoma markers MyoD1 and Myogenine and non-small cell lung cancers marker TTF-1." (PMID 27612448, 2016). "Furthermore, while all 10 MYOD1 mutant spindle cell and sclerosing rhabdomyosarcoma samples showed diffuse and strong MYOD1 immunoexpression, 7 of 31 samples of rhabdomyosarcoma with wild-type MYOD1 were negative for MYOD1 expression." (PMID 27562493, 2016). "Rhabdomyosarcoma usually express myogenic markers such as MyoD1 and desmin." (PMID 24349741, 2013). "Coexpression of desmin and nuclear myoD1 was only detected in rhabdomyosarcoma." (PMID 24349741, 2013).